PLEC (plectin)
Description:
Interlinks intermediate filaments with microtubules and microfilaments and anchors intermediate filaments to desmosomes or hemidesmosomes. Could also bind muscle proteins such as actin to membrane complexes in muscle. May be involved not only in the filaments network, but also in the regulation of their dynamics. Structural component of muscle. Isoform 9 plays a major role in the maintenance of myofiber integrity.
Synonyms: PCN; PLTN; HD1; PLEC1; EBS1; EBS5A; EBS5B; EBS5C; EBS5D; EBSMD; EBSND; EBSO; EBSOG; EBSPA; LGMD2Q; LGMDR17; PLEC1b
Tractability: Small molecule: a high-quality ligand is known; it has a binding pocket of medium quality. Antibody: its Gene Ontology location is reachable by antibodies, with high confidence. PROTAC: ubiquitination databases record sites on it; its protein half-life has been measured; a small molecule that binds it is known.
Target class: Structural protein
Gene: Protein-coding gene on chromosome 8 (143,915,152 to 143,976,734, reverse strand). Ensembl gene ENSG00000178209.
Subcellular location: Cytoplasm, cytoskeleton; Cell junction, hemidesmosome; Cell projection, podosome
Subcellular location (Human Protein Atlas): Cytosol; Intermediate filaments; Focal adhesion sites
Pathways (Reactome):
Cell-Cell communication: Type I hemidesmosome assembly
Extracellular matrix organization: Assembly of collagen fibrils and other multimeric structures
Programmed Cell Death: Caspase-mediated cleavage of cytoskeletal proteins
Gene Ontology:
Molecular function: ankyrin binding; cadherin binding; protein binding; RNA binding; structural constituent of cytoskeleton; structural constituent of muscle; actin binding; actin filament binding; cytoskeletal protein binding; dystroglycan binding; identical protein binding; structural molecule activity
Biological process: hemidesmosome assembly; intermediate filament cytoskeleton organization; wound healing; actin cytoskeleton organization; actin filament organization; actomyosin contractile ring assembly actin filament organization; adherens junction organization; cardiac muscle cell development; cell morphogenesis; cell motility; cellular response to fluid shear stress; cellular response to hydrostatic pressure; cellular response to mechanical stimulus; establishment of skin barrier; fibroblast migration; gene expression; intermediate filament organization; intracellular protein localization; keratinocyte development; keratinocyte differentiation; leukocyte migration involved in immune response; mitochondrion localization; mitochondrion organization; multicellular organism growth; myelination in peripheral nervous system; and 14 more
Cellular component: extracellular exosome; focal adhesion; hemidesmosome; intermediate filament cytoskeleton; sarcolemma; costamere; cytoplasm; cytosol; intermediate filament; perinuclear region of cytoplasm; plasma membrane; podosome; sarcoplasm; axon; brush border; cell periphery; contractile muscle fiber; cytoskeleton; mitochondrial outer membrane; myelin sheath; myofibril; Z disc
Genetic constraint (gnomAD): Loss-of-function variants: 216 observed, 333 expected, observed/expected ratio (o/e) 0.65, 90% interval 0.58 to 0.73. The synonymous counts are far from expectation, so gnomAD's model fits this gene poorly and the ratio says little. Missense variants: 6,863 observed, 6,265.9 expected, observed/expected ratio (o/e) 1.1, 90% interval 1.07 to 1.12. Synonymous variants: 3,621 observed, 2,828 expected, observed/expected ratio (o/e) 1.28, 90% interval 1.25 to 1.32.
Gene-disease validity (ClinGen):
ClinGen rates the evidence that PLEC causes each of these diseases.
PLEC-related muscular dystrophy-epidermolysis bullosa simplex spectrum disorder (autosomal recessive): Definitive. A spectrum of disease associated with loss or disrupted function of the PLEC gene.
Homologues: Orthologues: chimpanzee PLEC (99% identical), macaque PLEC (98% identical), rat Plec (93% identical), mouse Plec (93% identical), guinea pig PLEC (93% identical), pig PLEC (92% identical), dog PLEC (83% identical), tropical clawed frog plec (72% identical). Paralogues in human: MACF1 (23% identical), DSP (22% identical), DST (22% identical), EPPK1 (21% identical), SYNE1 (14% identical), SYNE2 (13% identical), DMD (11% identical), UTRN (11% identical), SPTBN4 (10% identical), SPTBN5 (10% identical), SPTBN2 (10% identical), SPTBN1 (10% identical), and 24 more.
Diseases named in the same sentence as PLEC in open-access papers:
PLEC is named in the same sentence as 154 diseases in open-access papers, as found by Europe PMC text mining. Sharing a sentence is not in itself a finding about the gene and the disease. The quoted sentences say what the papers report.
epidermolysis bullosa simplex (31 papers, 2010 to 2025). Epidermolysis bullosa simplex (EBS) is a group of hereditary epidermolysis bullosa (HEB) disorders characterized by skin fragility resulting in intraepidermal blisters and erosions that occur either spontaneously or after physical trauma. "In the MD group, we identified two variants (c.9343C>T and c.13192G>A) in the PLEC gene, which has been implicated in epidermolysis bullosa simplex with muscular dystrophies." (PMID 38818036, 2024). "In humans and mice, frameshift-inducing Krt14 mutations cause epidermolysis bullosa simplex, a disease characterized by skin blistering that can also be caused by mutations in Plectin." (PMID 36512409, 2023). "PLEC is expressed in various tissues, including muscles and fibroblasts, and PLEC deficiency causes epidermolysis bullosa simplex with muscular dystrophy (OMIM 226670), in which osteoporosis frequently develops." (PMID 37461309, 2023). "Via IFs, plectins link desmosomes to the nucleus, and mutations in plectin have been linked to epidermolysis bullosa simplex with muscular dystrophy." (PMID 36398718, 2022). "Plectin’s role in the cytoskeletal integrity and cell-cell contacts is evident in human patients with plectin mutations where disruption of keratin networks within the skin leads to extensive blistering or epidermolysis bullosa simplex." (PMID 36038818, 2022). "Most PLEC mutations cause epidermolysis bullosa simplex with muscular dystrophy (EBS-MD, MIM #226670), an autosomal recessive skin blistering disorder associated with progressive muscle weakness." (PMID 34572129, 2021). "Although mutations in plectin have been linked to epidermolysis bullosa simplex, muscular dystrophy, pyloric atresia, and several central nervous system malignancies, not much is known regarding plectin genetic defects in cancer." (PMID 34571895, 2021). "The most common neuromuscular phenotype associated with mutations in PLEC is epidermolysis bullosa simplex with muscular dystrophy (EBS-MD; MIM #226670)." (PMID 32605089, 2020). "Another severe LGMD type presenting with skin lesions together with congenital muscular dystrophy, myasthenic symptoms, and epidermolysis bullosa simplex is caused by plectin (PLEC1) mutations and should be considered in the different diagnosis." (PMID 27123443, 2016). "Autosomal recessive mutations in the cytolinker protein plectin account for the multisystem disorders epidermolysis bullosa simplex (EBS) associated with muscular dystrophy (EBS-MD), pyloric atresia (EBS-PA), and congenital myasthenia (EBS-CMS)." (PMID 22144912, 2011). "Similarly, the PLEC gene variants c.9343C>T and c.13192G>A, identified in the MD group, have been associated with epidermolysis bullosa simplex with muscular dystrophies." (PMID 38818036, 2024). "Mutations in PLEC cause epidermolysis bullosa simplex (EBS), which may be associated with myopathy or myasthenia." (PMID 35670010, 2022). "Mutations in the human plectin gene (PLEC) cause autosomal recessive epidermolysis bullosa simplex with muscular dystrophy (EBS‐MD)." (PMID 40641151, 2025). "Thus, intercellular spaces may be filled with interstitial fluid similar to edemas or the spontaneous skin blistering that occurs in patients with plectin mutations who develop epidermolysis bullosa simplex." (PMID 36038818, 2022). "As a multifunctional protein, plectin has been implicated in several multisystemic diseases, the most common of which is epidermolysis bullosa simplex with muscular dystrophy (EBS-MD)." (PMID 34572100, 2021). "The most common disease caused by mutations in the human plectin gene (PLEC) is epidermolysis bullosa simplex with muscular dystrophy (EBS‐MD), a rare autosomal skin blistering disorder associated with late‐onset muscular dystrophy." (PMID 32484610, 2021).
epidermolysis bullosa simplex (continued). "The most common disease caused by mutations in the human plectin gene (PLEC, NM_000445), epidermolysis bullosa simplex with muscular dystrophy (EBS-MD; OMIM 226670), is characterized by severe skin blistering and progressive muscular dystrophy." (PMID 26019234, 2015). "The most common disease caused by mutations in the human plectin gene, epidermolysis bullosa simplex with muscular dystrophy (EBS-MD), is characterized by severe skin blistering and progressive muscular dystrophy." (PMID 25447312, 2015). "Mutations in the PLEC gene cause basal epidermolysis bullosa simplex (EBS) in 8% of cases." (PMID 39500864, 2024). "Epidermolysis bullosa simplex (EBS), associated with intraepidermal blistering, is mainly caused by mutations within genes encoding keratin 5, 14, and plectin." (PMID 36091706, 2022). "However, there is a unique dominant plectin mutation, which leads to the disease epidermolysis bullosa simplex Ogna (EBS-Ogna), affecting skin exclusively." (PMID 22144912, 2011). "Epidermolysis bullosa simplex (EBS), a unique skin condition characterized by recurrent epidermal blistering following minor abrasions or bruises, is caused by mutations in the Plec1 gene that encodes for the outer mitochondrial membrane protein plectin." (PMID 32518230, 2020). "Plectin׳s function in strengthening cells against mechanical stress is unequivocally demonstrated by the severe tissue fragility of patients suffering from the most common plectin mutation-associated disease, epidermolysis bullosa simplex with muscular dystrophy (EBS-MD)." (PMID 25447312, 2015). "Plectin knockout or plectin mutations related to severe skin blistering disease (epidermolysis bullosa simplex) impair perinuclear keratin architecture, but not the linkages to the nucleus, nonetheless leading to misshapen nuclei and abnormal nuclear deformability." (PMID 28959689, 2017). "Dysfunction or absence of plectin leads to epidermolysis bullosa simplex (EBS), a skin blistering disease that in most cases is associated with muscular dystrophy." (PMID 23758845, 2013). "These phenotypes were similar to those reported for the first cases of patients lacking a functional plectin gene who suffered from epidermolysis bullosa simplex and muscular dystrophy (EBS-MD)." (PMID 34572100, 2021).
muscular dystrophy (31 papers, 2010 to 2025). Muscular dystrophy (MD) refers to a group of more than 30 genetic diseases characterized by progressive weakness and degeneration of the skeletal muscles that control movement. "All seven patients with mutations in PLEC had autosomal recessive (AR) disease, with four having clinically overt muscular dystrophy." (PMID 36578049, 2022). "All patients with intermediate AR-EBS with muscular dystrophy had at least one mutation in exon 31 (based on NM_000445), which encodes the rod domain of PLEC." (PMID 36578049, 2022). "Mutations of PLEC result in skin blistering and muscular dystrophy, with the tissue affected and the severity of the disease being determined by the site of the mutation." (PMID 30730609, 2019). "Mutations of the human plectin gene (PLEC) on chromosome 8q24 cause autosomal recessive epidermolysis bullosa simplex with muscular dystrophy (EBS-MD)." (PMID 27121971, 2016). "Most mutations in the plectin gene are inherited in an autosomal-recessive fashion resulting in EBS-MD (EBS with muscular dystrophy, MIM:226670), EBS-PA (EBS with pyloric atresia, MIM:612138), and EBS-CMS (EBS with congenital myasthenia)." (PMID 22144912, 2011). "This study demonstrates that plectin deficiency can indeed lead to both muscular dystrophy and pyloric atresia in an individual EBS patient." (PMID 20665883, 2010). "Mutations in the gene encoding plectin (PLEC) cause two distinct autosomal recessive subtypes of epidermolysis bullosa: EB simplex (EBS) with muscular dystrophy (EBS-MD), and EBS with pyloric atresia (EBS-PA)." (PMID 20665883, 2010). "Such plectin gene abnormalities cause not only PA but also muscular dystrophy." (PMID 39649513, 2024). "Moreover, regarding undiagnosed muscular dystrophies and neuropathies, additional plectin mutations (including isoform-specific mutations) can be expected to be identified in increasing numbers over the next few years." (PMID 34572129, 2021). "In humans, plectin (PLEC1) deficiency led to muscular dystrophy and pyloric atresia." (PMID 28181038, 2017). "While dKO mice suffered from an overall more severe form of muscular dystrophy compared to mdx or plectin-deficient mice, sarcolemmal integrity as well as glucose uptake of their myofibers were restored to normal levels upon ablation of plectin." (PMID 23758845, 2013). "Next, we asked whether an increase in Fhl2 positive myofibers of EOMs could be found across muscular dystrophies and therefore immunolabeled plecb−/− (plectin) and obscnb−/− (obscurin) mutant zebrafish EOMs, both resulting in muscular dystrophy when mutated in other models." (PMID 38431640, 2024). "However, subtle structural changes would not have been detected in these experiments and genetic mutations in the PLEC gene are associated with muscular dystrophy, characterized by the detachment of mitochondria from sarcoplasmic reticulum and mitochondrial clustering." (PMID 36479146, 2022). "Plectin (PLEC) encodes huge intermediate filament-binding protein and its mutation leads to EBS with muscular dystrophy." (PMID 32482619, 2020). "All plectin-related diseases are characterized by either muscular dystrophy or skin fragility, or a combination of both." (PMID 25447312, 2015). "However, this notion is clearly contradicted by our findings in patient 3, who - despite expressing rather high levels of rodless plectin in muscle – developed a severe form of muscular dystrophy." (PMID 27121971, 2016). "Our study also indicates that the mitochondrial pathology observed in plectin-deficient mouse skeletal muscle, and thus most likely also in plectinopathy patients, is a constitutive mechanism rather than a secondary effect of muscular dystrophy." (PMID 26019234, 2015). "Thus, for a more efficient rescue of muscular dystrophy in patients, therapeutic strategies aiming at a balanced expression of sarcolemmal levels of both, dystrophin and plectin, could prove useful." (PMID 23758845, 2013).
muscular dystrophy (continued). "Plectin is also prominently expressed in striated and smooth muscle cells, but its importance for the structure and function of muscle became only evident when patients with plectin-related EBS were found to suffer, in addition to skin blistering, from a late onset of muscular dystrophy." (PMID 25447312, 2015). "By comparing the histopathology of plectin/dystrophin dKO, mdx, and plectin cKO mice, it became clear that, overall, the additional lack of plectin in dKO mice was aggravating the muscular dystrophy phenotype of mdx mice, not at least because of the early death of double-deficient mice." (PMID 23758845, 2013). "Furthermore, as is distinctive for EBS-Ogna patients, the mutant mice did not develop muscular dystrophy, contrary to patients suffering from EBS-MD, the most common form of plectin-associated EBS." (PMID 22144912, 2011).
ovarian carcinoma (17 papers, 2011 to 2025). A malignant neoplasm originating from the surface ovarian epithelium. "Moreover, in epithelial ovarian cancer, high plectin expression has been shown to suppress EMT-associated migration by interfering with membrane receptor-mediated signaling." (PMID 41011568, 2025). "Previously, plectin was associated with cancer stem cell marker OCT4A in ovarian cancer." (PMID 34571895, 2021). "Increased plectin expression using IHC was also observed in recurrent HEY ovarian cancer cell line-derived mouse xenografts tissues compared to untreated control and paclitaxel-treated xenografts." (PMID 40565351, 2025). "Increased plectin protein levels were observed in type I (low-grade tumors) ovarian cancer tissues compared to type II (high-grade serous ovarian tumors)." (PMID 40565351, 2025). "Monoclonal antibodies targeting cancer-specific plectin reduced ovarian cancer cell migration increased chemosensitivity to cisplatin, and reduced tumor growth in mouse models." (PMID 40565351, 2025). "In several cancer types, including pancreatic and ovarian cancers, plectin has been shown to relocate from the cytoskeleton to the cell surface." (PMID 36612146, 2022). "In the same study, we showed enhanced expression of PLEC and vimentin in ovarian cancer cell lines after treatments with paclitaxel or cisplatin, which was consistent with increased expression of OCT4A in these cells." (PMID 34001250, 2021). "In this review article, we explore the roles of plakins, particularly plectin, periplakin and envoplakin in disease-states and cancers with emphasis on ovarian cancer." (PMID 34001250, 2021). "IHC analysis of patient specimens demonstrated strong plectin expression (>80%) at the cell membrane of serous, clear cell, and poorly differentiated ovarian cancer." (PMID 34571895, 2021). "In vitro, treatment with paclitaxel or cisplatin was shown to enhance plectin expression across different ovarian cancer cell lines (e.g., HEY, SKOV3, and OVCAR5)." (PMID 34571895, 2021). "The plectin-targeted peptide conjugated liposomes significantly decreased cell proliferation in the mice bearing OVCAR8 (epithelial ovarian cancer)." (PMID 34638660, 2021). "For example, plectin-targeted liposomes enhance the therapeutic efficacy of a PARP inhibitor (AZ7379) in the treatment of ovarian cancer in animal models." (PMID 31534547, 2019). "Similarly, abnormal overexpression of plectin has been reported in reproductive cancers, such as prostate cancer, testicular cancer, and ovarian cancer." (PMID 41011568, 2025). "Moreover, plectin-targeted liposomes enhanced the therapeutic efficacy of PARP inhibitors in ovarian cancer treatment." (PMID 40565351, 2025). "Notably, plectin expression in ovarian cancer appears to follow a dynamic pattern: it is upregulated during early tumorigenesis but subsequently downregulated as the disease progresses to high-grade or advanced stages." (PMID 41011568, 2025). "However, plectin was down-regulated in chemoresistant ascites-derived ovarian cancer cells by proteomics analyses." (PMID 40565351, 2025). "Plectin’s ability to promote cell proliferation and invasion was previously demonstrated in pancreatic ductal adenocarcinoma, non-small-cell lung cancer, high-grade epithelial ovarian cancer, prostate cancer, and head and neck squamous cell carcinoma." (PMID 38263015, 2024). "Interestingly, in ovarian cancer, a proteomic study investigating makers of peritoneal metastasis found that plectin secretion was enriched during cancer–peritoneal interaction." (PMID 34571866, 2021). "Proteomic analysis of non-adherent cancer cells derived from ascites of advanced-stage ovarian cancer patients found that plectin expression was significantly higher in samples from chemonaïve patients at diagnosis compared to patients with recurrent disease after chemotherapy." (PMID 34571895, 2021). "Plectin is a protein that is mislocalized on the surface of ovarian cancer cells." (PMID 34638660, 2021).